MC4R (melanocortin 4 receptor)
Diseases named in the same sentence as MC4R in open-access papers (continued):
Sharing a sentence is not in itself a finding about the gene and the disease.
Hyperinsulinemia (46 papers, 2009 to 2026). An increased concentration of insulin in the blood. "Previous studies have described the clinical features of MC4R deficiency as hyperphagia (increased drive to eat), weight gain in the first 5 years of life, disproportionate hyperinsulinemia and accelerated linear growth in childhood." (PMID 41102563, 2025). "Studies have shown that the phenotypic features of the loss of function of MC4R in children are increased fat and lean masses, increased linear growth, increased bone mineral density, hyperphagia, and hyperinsulinemia." (PMID 40001512, 2025). "Mice deficient for Mc4r develop a maturity-onset obesity syndrome associated with hyperphagia, hyperinsulinemia, and hyperglycemia." (PMID 37638032, 2023). "Sim1- and MC4R-expressing neurons control insulin secretion by regulating autonomic tone, and deficiency of Sim1 or MC4R results in hyperinsulinemia in mice and humans." (PMID 36175420, 2022). "MC4R mutations have been associated with increased BMI, increased lean mass, increased linear growth, hyperphagia, and hyperinsulinemia; a condition collectively classified as MC4R deficiency or termed the MC4R syndrome." (PMID 32921795, 2021). "Mice and humans with MC4R mutations also experience hyperinsulinemia that exceeds their degree of adiposity due to the role MC4R in the suppression of insulin release." (PMID 28829041, 2017). "Mc4r-deficient mice have hyperinsulinemia and hyperinsulinemia stimulates expression of lipogenic genes such as SREBP-1c and PPARγ in liver." (PMID 28030540, 2016). "Obese patients with Mc4r mutations have smaller prevalence of hypertension, reduced BP and reduced norepinephrine secretion, despite being severely obese and showing severe metabolic abnormalities, such as hyperphagia and hyperinsulinemia." (PMID 34512392, 2021). "Mutations in MC4R are associated with hyperphagia, severe childhood obesity, and hyperinsulinemia." (PMID 33192474, 2020). "It is conceivable that during early weight loss, SDV alters the set point due to reversal (or normalization) of the underlying hyperinsulinemia in Mc4r−/− mice as a result of denervation of the insulin-secreting cells of the pancreas, and presumably depletion of hepatic glycogen stores." (PMID 29545738, 2018). "The phenotype common to MC4R mutation carriers is hyperphagia within the first year of life leading to severe childhood obesity, increased lean mass, increased linear growth, and extreme hyperinsulinemia." (PMID 27738543, 2016). "Based on studies including children with damaging MC4R mutations, specific characteristics have been associated with MC4R deficiency, namely increased fat and lean mass, increased linear growth, increased bone mineral density, hyperphagia, and hyperinsulinemia." (PMID 32921795, 2021). "Our comparison of BW-matched animals revealed that hepatic DNL, FAO, and steatosis as well as hyperphagia, hyperinsulinemia, and hepatic upregulation of lipogenic enzymes were more pronounced in ob/ob mice compared with Mc4r-KO mice." (PMID 37681411, 2023). "Hyperinsulinemia, though significantly more pronounced in individuals with LEPR or MC4R deficiency compared with those with LEP deficiency, increased with age in all three mutant groups." (PMID 37659411, 2023). "Conversely, interruption of melanocortin neural circuits should increase efferent vagal activity, as is evident by the increase in hyperinsulinemia in Mc4r−/− mice." (PMID 29545738, 2018). "At the age of 10–15 years, hyperinsulinemia appeared milder in the group with LEP deficiency as compared with the patients with LEPR and MC4R deficiencies (mean 49 versus 104 and 66 μIU/mL in children with LEP, LEPR, or MC4R deficiency, respectively) (range of insulin assay: 0–300 μIU/mL)." (PMID 37659411, 2023).
Hyperinsulinemia (continued). "MC4R deficiency has also been reported to be associated with an increase in linear growth velocity attributable to hyperinsulinemia and the absence of the suppression of growth hormone levels that is usually seen in other forms of obesity." (PMID 34045736, 2021). "Similar effect of MC4R activation could also be observed in hyperinsulinemia-induced hypertension." (PMID 34512392, 2021). "Hyperinsulinemia in WD-fed MC4R KO mice might further accelerate the development of steatosis." (PMID 31990961, 2020). "In MC4R knock-out mice, to the contrary, GH and IGF-1 suppression was observed recovered when hyperphagia was prevented and hyperinsulinemia reversed." (PMID 34177811, 2021). "In fasted WD-fed MC4R-KO mice after 8 weeks of CANA treatment, hyperglycemia and hyperinsulinemia were markedly improved." (PMID 29402900, 2018). "Therefore, while the effects of Mc4r deletion on peripheral vascular resistance may be cardioprotective, other aspects of the Mc4r obesity syndrome, such as hyperinsulinemia, incomplete growth hormone suppression, and altered autonomic tone are potentially cardiotoxic." (PMID 28829041, 2017). "CANA significantly improved hyperglycemia and hyperinsulinemia with increased urinary excretion at 8 weeks of treatment in non-fasted MC4R-KO mice fed a WD." (PMID 29402900, 2018).
Hypertension (35 papers, 2013 to 2025). The presence of chronic increased pressure in the systemic arterial system. "MRAP2 mice lack the early-onset hyperphagia of MC4R knockout mice, and humans with MRAP2 genetic variants exhibit hyperglycaemia, hypertension and high blood cholesterol more frequently than those with MC4R mutations." (PMID 39574659, 2024). "Administration of LY2112688 yielded a higher incidence of hypertension in the MC4R-deficient group than the control group." (PMID 36012526, 2022). "Consistently, clinical observation of obese Mc4r haploinsufficient patients showed that MC4R loss-of-function causes a significantly lower prevalence of hypertension." (PMID 34512392, 2021). "Compared to equally obese control subjects, the prevalence of hypertension in MC4R-deficient people was significantly lower, and MC4R-deficient patients exhibited lower increases in heart rate upon waking." (PMID 32166324, 2020). "As far as we know, this is the first study showing the association of a common genetic variant near MC4R gene with blood pressure in patients with hypertension." (PMID 23849767, 2013). "Hyperglycaemia and hypertension have been reported to occur more commonly in individuals with MRAP2 mutations than in those with MC4R mutations, which led to the suggestion that MRAP2 variants may affect signaling by other GPCRs." (PMID 41401256, 2025). "One group also reported hyperglycaemia and hypertension occurred more commonly in individuals with MRAP2 mutations than in those with MC4R and suggested that MRAP2 variants may affect signaling by other GPCRs." (PMID 39574659, 2024). "Analyses conducted by gender showed that in addition to the association of neck circumference with MC4R genotype, the trend toward higher waist circumference and Lipid Accumulation Product suggest an effect of the risk allele C on visceral obesity in women with hypertension." (PMID 23849767, 2013). "MRAP2 knockout mice lack the early-onset hyperphagia of MC4R knockout mice, and humans with MRAP2 genetic variants exhibit hyperglycaemia, hypertension and high blood cholesterol more frequently than those with MC4R mutations." (PMID 41401256, 2025). "Increased levels of the Melanocortin-4 receptor (Mc4r) in the paraventricular nucleus of the hypothalamus have been shown to mediate hypertension in the offspring born to obese mothers." (PMID 37836490, 2023). "Antagonism of the MC4R reduces obesity-related hypertension and renal sympathetic nerve activity (RSNA)." (PMID 35807782, 2022). "In the present study, we investigated the association of FTO and MC4R gene polymorphisms with hypertension in the Chinese Han population and analysed the relationship between FTO rs9939609 and MC4R rs17782313 variants." (PMID 26324055, 2016). "The UK Biobank MC4R variant carriers also had a lower risk of hypertension for a given BMI compared to noncarriers and lower self-reported use of blood pressure-lowering medication." (PMID 41102563, 2025). "As seen in morbid obese - with no hypertension and with rare mutations in MC4R gene, this sample of hypertensive individuals carrier of risk allele C for common variant near MC4R had lower levels of blood pressure in comparison to homozygote non-carriers." (PMID 23849767, 2013). "Common genetic variants of FTO rs9939609 have positive associations with BMI and neck circumference and MC4R rs17782313 in women, but a negative association with diastolic and mean blood pressure in men with hypertension." (PMID 23849767, 2013). "While MC4R knockout mice have been available for some time, the rat provides a new opportunity to obtain higher resolution phenotypes (longer measurements of blood pressure, more robust hypertension, more easily obtained blood flow measurements) that are difficult to obtain in mice." (PMID 24400148, 2013).
Hypertension (continued). "Leptin, acting on melanocortin four receptors (MC4R) in the paraventricular nucleus of hypothalamus (PVN), appears to be required for early-life programming of hypertension arising from either maternal obesity or neonatal hyperleptinemia." (PMID 40356772, 2025). "In contrast to the protective effects of female sex hormones against the development of hypertension, chronic dihydrotestosterone (DHT) treatment in female rats induced an increase in BP through activation of the SNS and hypothalamic MC4R." (PMID 40356772, 2025). "Chronic hyperleptinemia stimulates the tonic firing rate of MC4R-expressing PVH neurons, resulting in hypertension." (PMID 35807782, 2022). "The effects of MC4R and FTO on daytime hypertension were first investigated independently of each other." (PMID 26324055, 2016). "MC4R agonists, designed to stimulate the MC4R in place of the POMC ligands, are a well-researched therapeutic route that reduces adiposity and appetite; however, most of these agonists have cardiovascular drawbacks, such as hypertension." (PMID 36012526, 2022). "Others have found that MC4R signaling mediates hypertension in those non-pregnant female offspring derived under maternal obesity." (PMID 32817646, 2020). "Although these factors are not evaluated in this study, it is shown that hypertension and cardiovascular disease, which are other metabolic disorders related to PCOS, have an association with high expression of MC4R in the other rat models of PCOS." (PMID 34466430, 2018). "In response to ganglionic blockade with mecamylamine, blood pressure and hindlimb resistance fell more in MC4R KO rats, suggesting that sympathoactivation of the vascular was still evident, despite the absence of hypertension." (PMID 24400148, 2013). "However, the same study also showed that MC4R antagonism was not effective in lowering BP in angiotensin-II-induced hypertension, indicating MC3/4R-independent mechanisms in SNA modulation." (PMID 34512392, 2021). "In contrast, in female SHR, estrogens do not contribute to the hypertension, but the sympathetic nervous system, renal nerves, and the RAS do contribute, although sympathetic activation is not mediated by MC4R activation." (PMID 24844641, 2014).
Anxiety (26 papers, 2012 to 2025). Intense feelings of nervousness, tension, or panic often arise in response to interpersonal stresses. "This study underscores the therapeutic potential of targeting MC4R as a treatment, highlighting its role in mitigating anxiety-like behaviors associated with ELS." (PMID 40015967, 2025). "The important role of MC4R allows for it to be considered as a target for the development of drugs for the treatment of stress-associated diseases, such as anxiety and depression." (PMID 37047638, 2023). "Because sexual function can be negatively affected by anxiety, we conducted an open field test to see if loss of MC4R increased anxiety-like behaviors." (PMID 37033219, 2023). "Given this relationship, MC4R may represent a potential therapeutic target for addressing stress-associated conditions such as anxiety and depression." (PMID 40281288, 2025). "However, GABA-ergic stimulation and suppression of the 5-HT3R within the MC4R neurons in the bed nucleus causes cessation of the effect of the high-fat diet-induced anxiety and depression." (PMID 36004833, 2022). "This suggests that ACTH's beneficial effects on anxiety are mediated through MC4R activation in both neuronal and astrocytic populations." (PMID 40015967, 2025). "Depression is associated with weight loss and decreased appetite; MC4R signaling has an impact on feeding behavior, pain, drug addiction, regulation of HPA axis activity, emotional states, anxiety, and depression." (PMID 39962033, 2025). "Both stressors resulted in a reduction of food intake and an increase in anxiety-like behavior, effects that were entirely inhibited by the administration of a melanocortin receptor type 4 (MC4R) antagonist." (PMID 41321745, 2025). "Our findings also show that knocking-in MC4R in either neurons or astrocytes was able to rescue the anxiety-like behavior after ACTH treatment." (PMID 40015967, 2025). "In the light/dark box task, ACTH treatment decreased anxiety in both the animals with MC4R reexpressed in neurons and animals with the receptor reexpressed in astrocytes." (PMID 40015967, 2025). "Our study investigated ACTH's effect on anxiety, showing MC4R-dependent improvements, which challenge the notion that ACTH's primary effects are mediated through MC2Rs in the adrenal cortex for systemic glucocorticoid release." (PMID 40015967, 2025). "On the other hand, numerous studies have also demonstrated that signaling through MC4Rs causes depression-like, anxiogenic, and anti-reward effects, while ICV injection of MC4R antagonists reduces depressive and anxiety-like behaviors." (PMID 38248278, 2024). "ICV administration of MC4R antagonists was shown to block the anxiety-like behavior induced by ethanol withdrawal and prevent reinstatement of nicotine seeking triggered by footshock stress." (PMID 38248278, 2024). "Nevertheless, accumulating evidence in the last ten years showed that MC4R is involved in the regulation of anxiety and the neurobiology of depression." (PMID 36123585, 2022). "GABAergic projections from AgRP neurons to the melanocortin 4 receptor (MC4R) neurons located in the dBNST modulates high-fat diet (HFD)-induced anxiety and depression-like responses." (PMID 33767348, 2021). "Evidence from animal models links the MC4R to eating behavior in stress-induced anxiety-like or depression-like behavior, anhedonia, and corticosterone secretion." (PMID 32373164, 2020). "We investigated the immunohistochemical alterations of the hippocampal neuropeptide Y (NPY) and melanocortin 4 receptor (MC4R) neurons, as a possible underlying mechanism in a modulation of anxiety-like behavior in rats." (PMID 30863280, 2019). "The impact of central melanocortin system in the regulation of anxiety and depression levels was confirmed following intracerebroventricular administration of selective MC4R antagonist in rats." (PMID 30863280, 2019).
Anxiety (continued). "Infusion of a selective MC4R agonist into the medial amygdala elicits anxiety in the elevated plus-maze test and decreases food intake." (PMID 27213003, 2016). "MC4R facilitates an increase in anxiety-like and depression-like behaviors pursuant to chronic stress." (PMID 27213003, 2016). "This study explores the hypothesis that recurrent ELS is associated with long-term anxiety and that treatment with ACTH can prevent this anxiety through a mechanism that involves the melanocortin 4 receptor (MC4R) in the brain." (PMID 40015967, 2025). "Furthermore, MC4R-expressing neurons in the MeA were activated by acute stress exposure and inhibiting MC4Rs locally in the MeA abolished stress-induced anxiety-like behavior." (PMID 41321745, 2025). "MC4R may be a possible therapeutic target in the treatment of stress-related disorders such as anxiety and depression." (PMID 39962033, 2025). "This supports the role of MC4R in both neuronal and astrocytic populations in modulating anxiety responses following ELS; however, the expression of MC4R in astrocytes appears to have a greater impact, with less anxiety, after ELS compared with its expression in neurons." (PMID 40015967, 2025). "Blocking MC4R may be useful in treating patients with stress-related disorders such as anxiety and depression, and MC4R is a possible therapeutic target." (PMID 40281288, 2025). "MC4R signaling in the dorsal raphe nucleus affects anxiety and depression-like behavior." (PMID 37047638, 2023). "And activation of MC4R signaling contributes to anxiety and depressive‐like behavior." (PMID 36510669, 2023). "Additionally, Mc4r is downregulated in the hippocampus at 3 months old and facilitates anxiety- and depression-like behaviours pursuant to chronic stress." (PMID 33795014, 2021). "While such IgG are not pathogenic themselves, their cross-reactivity with α-MSH may lead to an increased production of immune complexes, with α-MSH overactivating the MC4R and resulting in increased satiety and anxiety of ED patients." (PMID 32272706, 2020). "Several studies have implicated MC4R in anxiety and stress situations but do not identify the exact mechanism involved." (PMID 26629487, 2015). "Central administration of MC4R agonist increases anxiety behaviors." (PMID 26629487, 2015). "A higher rate of anxiety and compulsiveness in patients with AN might be mediated by the MC4R." (PMID 32373164, 2020). "The fact that the most significant (positive) correlation between NPY/MC4R ratio and the anxiety unequivocally confirms that this new parameter could be, due to its highest significance, a useful tool for estimation of anxiety level in behavioral investigations." (PMID 30863280, 2019). "Our findings underscore a crucial role for MC4R in ACTH's positive effects and its potential to alleviate anxiety-like behavior." (PMID 40015967, 2025). "Chronic administration of a high-fat diet blunts AgRP response to anxiety and depression signals, as well as hunger by reducing GABA-ergic outputs from AgRP aimed at MC4R." (PMID 36004833, 2022). "To date, only MC3R and MC4R with their ligand, the alfa-MSH (also gamma-MSH in the case of MC3R) were connected to anxiety and depression." (PMID 36004833, 2022). "Our findings reveal that ACTH ameliorates anxiety-like behavior associated with ELS, without altering seizure parameters, in wild-type but not in male and female MC4R knock-out mice." (PMID 40015967, 2025). "The changes in astrocyte protein expression after ELS and the ability of ACTH to improve chronic anxiety in WT mice, but not in KO mice, raised a question about the impact of neuronal and glial MC4R expression on ACTH’s positive effects." (PMID 40015967, 2025). "The melanocortin system, principally via MC4R, has been demonstrated to play a central role in stress response and negative emotional states, including anxiety and depression, suggesting the MC4R as a possible target to treat these psychiatric conditions." (PMID 33202557, 2020).